CRP (C-reactive protein)
Diseases named in the same sentence as CRP in open-access papers (continued):
Sharing a sentence is not in itself a finding about the gene and the disease.
atherosclerosis (continued). "Moreover, atherosclerosis was not reduced in CRP-deficient mice, providing evidence against a proatherogenic role of CRP." (PMID 27258004, 2016). "In addition, this combination of hypoadiponectinemia and increased CRP might contribute to the development of atherosclerosis." (PMID 25873951, 2015). "Through the activation of the classical complement pathway, cytokine production, and complement-related inflammatory response, CRP will accelerate the acute inflammatory injury, which may also promote the formation of atherosclerosis thrombus and the occurrence of complications." (PMID 26609318, 2015). "In addition, plasma pentosidine was strongly correlated with the markers of inflammation, such as CRP, fibrinogen and IL-6 and the levels of soluble vascular cellular adhesion molecule-1 (sVCAM-1) which play an important role in the development of atherosclerosis." (PMID 26645467, 2015). "In addition to CRP, CD36 is one of the key genes enriched in the cell surface binding pathway, and has been reported to be associated with inflammation-mediated diseases such as atherosclerosis." (PMID 24763700, 2014). "CRP level may also predict the progression of atherosclerosis." (PMID 25192283, 2014). "This study came to the conclusion that genetically elevated CRP levels do not increase the risk of ischemic vascular disease, suggesting that CRP might be a bystander rather than a causal factor in the progress of atherosclerosis." (PMID 24808639, 2014). "Notably, CRP level is not related to the risk of developing venous thrombosis, a vascular condition typically independent of atherosclerosis." (PMID 23983803, 2013). "The aim of this study was to evaluate whether poor oral hygiene is associated with carotid and popliteal arterial intima–media thickness, which is one of the predictors of future progression of sub-clinical atherosclerosis, and high-sensitivity C-reactive protein (hsCRP) and fibrinogen levels." (PMID 23982836, 2013). "Therefore, CRP may be an important therapeutic target for the prevention and treatment of atherosclerosis." (PMID 23111890, 2013). "Raised levels of C-reactive protein (CRP) have been implicated as a risk marker for atherosclerosis and CVD in many studies, although it is not clear if CRP could play a causative role." (PMID 23635324, 2013). "The increase in the risk of ischemic vascular disease associated with higher plasma CRP levels observed in epidemiological studies may not be causal, but rather that increased CRP levels are simply a marker for atherosclerosis and ischemic vascular disease." (PMID 21430962, 2011). "Additionally, CRP which has recently emerged as one of the most important inflammatory mediators can directly participate in the pathogenesis of atherosclerosis by activating endothelial cells and promoting the inflammatory component of atherosclerosis." (PMID 21214952, 2011). "It is thus important to clarify, whether when raised levels of CRP arise from a non-vascular cause (i.e. a stimulus for CRP other than atherosclerosis), CRP retains its association with CVD." (PMID 20436910, 2010). "Interestingly, CRP has been suggested to directly influence atherosclerosis." (PMID 18384670, 2008). "C-reactive protein (CRP) is a non-specific marker of systemic inflammation, but whether it plays a causal role in atherosclerosis and its complications remains controversial." (PMID 18714381, 2008). "Although our investigation minimized confounding factors by excluding for cardiovascular disease and controlling for many primary risk factors of atherosclerosis, we did not adjust for the possible influence of secondary risk factors, such as C-reactive protein or other inflammatory markers." (PMID 17386093, 2007).
atherosclerosis (continued). "Systemic signs of inflammation, as wall and serum C-reactive protein, similar to those found in atherosclerosis, are present in patients with degenerative aortic valve stenosis and may be expression of a common disease, useful in monitoring of stenosis progression." (PMID 16774687, 2006). "This state not only accelerates the oxidation of phospholipids but also promotes the accumulation of serum amyloid A and C-reactive protein (CRP), thereby impairing HDL’s innate protective role against atherosclerosis." (PMID 40276550, 2025). "Elevated 1-MNA was associated with increased systemic inflammation (high-sensitivity CRP) and reduced high-density lipoprotein cholesterol, suggesting that NNMT influences atherosclerosis progression through both metabolic and inflammatory mechanisms." (PMID 41008588, 2025). "However, it does not account for medication use (e.g., statins and antihypertensives), which can modify this risk, nor does it exclude individuals with preclinical atherosclerosis, prior cardiovascular procedures, or high C-reactive protein levels, all of which can influence stroke or MI." (PMID 40431346, 2025). "This abundance of pro-inflammatory cytokines, together with high levels of C-reactive protein (CRP), accelerates the development and progression of atherosclerosis, a key phenomenon in the onset of cardiovascular diseases (CVD)." (PMID 41010664, 2025). "In another study, it was demonstrated that the CAR predicts atherosclerosis and is valuable for CAD diagnosis, outperforming those of CRP and albumin individually." (PMID 39854741, 2025). "In animal models of atherosclerosis, DPP-4is lower circulating CRP, MCP-1, IL-6, and TNF-α while raising the anti-inflammatory IL-10." (PMID 41462689, 2025). "Atherosclerosis and CVD are known to induce low-grade systemic inflammation, leading to minor elevations in hs-CRP levels." (PMID 40004724, 2025). "Although hepatocellular carcinoma (HCC) is not a direct cause of atherosclerosis, it can contribute to thrombosis and the establishment of a pro-inflammatory microenvironment, characterized by elevated levels of C-reactive protein (CRP), fibrinogen, and interleukin-6 (IL-6)." (PMID 40936714, 2025). "In atherosclerosis and heart failure, endothelial dysfunction and plaque progression are driven by inflammatory cytokines (TNF-α, IL-6, CRP, etc.)and reactive oxygen species (ROS)." (PMID 41462689, 2025). "Curcumin has been shown to inhibit the expression of pro-inflammatory mediators, such as C-reactive protein (CRP), TNF-α, IL-1β, and intercellular adhesion molecule-1 (ICAM-1), which play crucial roles in the development and progression of atherosclerosis." (PMID 39941147, 2025). "C-reactive protein (CRP) is a common biomarker of systematic inflammation that can induce subintimal cholesterol deposition and facilitate atherosclerosis development." (PMID 41333918, 2025). "The studies vary in population size and focus, but collectively support the role of inflammation, as indicated by elevated CRP levels, in the pathogenesis and prognosis of T2DM and atherosclerosis." (PMID 40725102, 2025). "Chronic Mg deficiency leads to enhanced baseline inflammation driven by elevated cytokines like IL-6 and C-reactive protein (CRP) and therefore plays a central role in atherosclerosis." (PMID 39408157, 2024). "Inflammatory cytokines such as C-reactive protein (CRP) and interleukins are elevated in patients with atherosclerosis and endothelial dysfunction." (PMID 39129923, 2024). "In conclusion, TNF-α inhibitors are highly effective in reducing atherosclerosis progression in psoriasis patients, consistently improving vascular health markers like CIMT, aPWV, FAI, and CRP." (PMID 39739136, 2024). "IL6, TNF-α, IL1, and c-reactive protein (CRP)) in the aorta, reducing the infiltration of inflammatory cells (macrophages) into the intima, thereby reducing atherosclerosis and plaque formation." (PMID 38799425, 2024).
atherosclerosis (continued). "The inverse correlation between CRP and HDL has been previously reported in patients with atherosclerosis, non-small-cell lung carcinoma, cardiovascular disease treated with lipid-modifying therapies, and AMD." (PMID 38333436, 2024). "Neutrophil–lymphocyte ratio (NLR), C-reactive protein (CRP), and serum albumin (ALB) are established indicators of inflammation and atherosclerosis pathogenesis." (PMID 38982273, 2024). "For example, one study associated H. pylori infection with elevated inflammatory markers like C-reactive protein (CRP) and interleukin-6 (IL-6), which contribute to endothelial dysfunction and atherosclerosis progression." (PMID 39202269, 2024). "Inflammatory markers, such as C-reactive protein (CRP), are often elevated in individuals with T1D, indicating an ongoing inflammatory response that can lead to vascular injury and atherosclerosis." (PMID 39246894, 2024). "CRP was found together with LDL particles and macrophages within atherosclerotic plaques in people with atherosclerosis." (PMID 39329916, 2024). "In atherosclerosis and coronary heart disease, an HFD elevates IL-6, C-reactive protein (CRP), and TNF-α preceding endothelial dysfunction and nitric oxide depletion." (PMID 38999835, 2024). "There was a significant association of clinical periodontal parameters, proinflammatory cytokines, hs-CRP, and LDL with carotid ITM as a measure of subclinical atherosclerosis." (PMID 36983201, 2023). "Previous studies show that LPC levels are inversely correlated with plasma CRP and LPC has the ability to bind CRP, resulting in delayed progression of atherosclerosis." (PMID 37686719, 2023). "A CRP mutant can bind to atherogenic LDL, is reported to have atheroprotective role in a murine model of atherosclerosis." (PMID 37860004, 2023). "PAA is also derived using chronological age and nine clinical biomarkers such as C-reactive protein (CRP), a systematic biomarker of inflammation that plays an important role in the pathology of atherosclerosis." (PMID 37889500, 2023). "Through acute-phase proteins such as CRP or cytokines such as TNF-α and IL-6, chronic inflammation greatly contributes to atherosclerosis in both the tunica intima and tunica media layers of the arterial wall." (PMID 37893519, 2023). "The local inflammation process results in systemic elevations of cytokines and proinflammatory proteins such as C-reactive protein (CRP), atherosclerosis, osteoporosis due to systemic inflammation, or increased risk of developing malignant neoplasms." (PMID 36835215, 2023). "To date, anti-inflammatory therapy in atherosclerosis has targeted the NLRP3 inflammasome and upstream links of the IL-1β/IL-6/CRP axis." (PMID 36768404, 2023). "Data obtained in table showed that, there was a significant elevation in the levels of CRP, IL-6 and TNF-α in obese with atherosclerosis patients and obese subjects compared with control group (p < 0.001)." (PMID 36407366, 2022). "In addition, CRP was also suggested to take part in the neovascularization of intima in vulnerable plaques which could contribute to its destabilization and progression of atherosclerosis." (PMID 35625480, 2022). "It is unclear what role CRP plays in the transition between VSMC proliferation and death during atherosclerosis." (PMID 35178859, 2022). "Reduced anti-inflammatory cytokine levels, such as CRP, together with lower LDL-C and TC levels, inhibited the development of atherosclerosis." (PMID 36262168, 2022). "C-reactive protein (CRP) is the most reactive serum protein of acute-phase inflammation and one of the most important prognostic biomarkers of atherosclerosis and cardiovascular disease (CVD)." (PMID 35563860, 2022). "CRP can bind to LDL-C in atherosclerotic plaques, leading to complement activation, and promoting inflammation and atherosclerosis." (PMID 35407457, 2022).
atherosclerosis (continued). "C-reactive protein (CRP), an acute phase protein and biomarker of systemic inflammation, has been associated with different cardiovascular diseases and has an established diagnostic and prognostic role in atherosclerosis; less is known about its role in non-ischemic cardiomyopathies." (PMID 36498643, 2022). "One of the acute-phase reactants, C-reactive protein (CRP), has been pointed out as an important biomarker for atherosclerosis and acute myocardial infarction." (PMID 35428187, 2022). "We also detected the level of CRP (C-reactive protein) in ApoE−/−+PBS and ApoE−/−+EPA group to show the effects of EPA in atherosclerosis." (PMID 35464772, 2022). "The levels of low-density lipoprotein cholesterol (LDL-C), homocysteine (Hcy), and C-reactive protein (CRP) exhibited significant differences between the healthy control group and patients with atherosclerosis (P < 0.05)." (PMID 35235755, 2022). "Ovsepyan found that macrophages secreted large amounts of C-reactive protein (CRP) and TNFα, IL-6, and other proinflammatory factors, promoting the apoptosis of smooth muscle cell and the development of atherosclerosis." (PMID 35003306, 2021). "This is in accordance with previous studies exploring CRP value in CKD patients and its role in the pathogenesis of chronic inflammation, especially in the context of the malnutrition, inflammation, and atherosclerosis (MIA) syndrome." (PMID 33660959, 2021). "In this study, MPO variably and positively correlated with CRP, IMT and PWV supporting its role in RA-related inflammation and atherosclerosis." (PMID 34680168, 2021). "The identification of MIAS was based on one or more of the following three conditions: C-reactive protein (CRP)≥10 mg/L, malnutrition–inflammation score (MIS)> 7, and the presence of atherosclerosis-related medical records." (PMID 33413177, 2021). "Its sublingual immunization suppressed vascular lesion formation by reducing the expressions of CRP, MCP-1, and ox-LDL; therefore, this vaccine was suggested as a promising therapeutic factor to suppress P. gingivalis-mediated atherosclerosis." (PMID 33976982, 2021). "Third, bilirubin is negatively correlated with inflammatory markers, such as C-reactive protein, neutrophil-leukocyte ratio, and red cell distribution width, indicating that bilirubin could reduce pro-inflammatory cytokines and might also inhibit the inherent inflammatory process of atherosclerosis." (PMID 34512527, 2021). "Other markers of inflammation such as C-reactive protein (CRP) can help with the prediction of clinical and subclinical atherosclerosis and play a major role in the identification of brain hemorrhage and conditions of stroke." (PMID 34299052, 2021). "Atherosclerosis-induced CAD is an inflammatory process, and the serum CRP level, as a marker of inflammation, correlates with disease severity and plaque width." (PMID 33453709, 2021). "Inflammation is the hotbed for atherosclerosis and the pro-inflammatory interleukin (IL) 1β-IL6-C-reactive protein (CRP) pathway is the central axis." (PMID 33350884, 2021). "Isoflavone treatment for 12 weeks reduced serum high-sensitivity (hs)-C-reactive protein (CRP) levels and improved brachial flow-mediated dilatation in patients with clinically manifested atherosclerosis and prior ischemic stroke." (PMID 34445360, 2021). "As a result, when considering its interactions with atherosclerosis conditions such as that occurring in acute ischemic stroke, PTX3 appears to be of superior prognostic value as compared to CRP in the LAA subgroup." (PMID 33210471, 2021).
atherosclerosis (continued). "For instance, IL-6 stimulates AGT, FBG, CRP, SAA and several complement factors’ synthesis that propagate the downstream inflammatory response responsible for atherosclerosis." (PMID 33407555, 2021). "Regular endurance exercise has been shown to reduce biomarkers associated with chronic, vascular inflammation and the development of atherosclerosis such as tumor necrosis factor alpha (TNF-α), interleukin 6 (IL-6) and C-reactive protein (CRP)." (PMID 34571843, 2021). "RESULTS: SDF1, MMP12 and CRP were elevated in patients with clinical atherosclerosis, but after controlling by confounding factors, only SDF1 and CRP remained increased." (PMID 34062730, 2021). "Notably, these two conditions are associated with increased levels of C-reactive protein, interleukin-6, plasmin-antiplasmin complex, factor VII, and factor VIII, which by inducing inflammation and hypercoagulability may further promote atherosclerosis progression and thrombosis." (PMID 32397347, 2020). "The body weight, TC, LDL-C, HDL-C, AI, WBC counts, as well as CRP and TNF-α levels, were significantly increased in the atherosclerosis group compared to the NC group (P < 0.05, P < 0.01), except for TG." (PMID 32213192, 2020). "CRP further increased the transcytosis of LDL across endothelial cells and LDL retention in vascular walls, which promoted atherosclerosis." (PMID 32410858, 2020). "Several studies described the predictive value of the C-reactive protein (CRP), IL-6, and TNF-α on atherosclerosis development." (PMID 32230840, 2020). "As well, we found that the frequency of cTfh1 cells negatively correlated with CRP and ESR, while the positive correlation between CRP and ESR and frequency of cTfh2 and cTfh17 cells existed in advanced atherosclerosis (patients with stenosis ≥50%)." (PMID 33230950, 2020). "Among the proposed techniques of detecting subclinical atherosclerosis, we evaluated the cIMT and ASI, as well as the biomarkers LDL, HDL, Chol, CRP, TGL, HBA1c, and creatinine." (PMID 30646893, 2019). "The present study investigated the involvement of Chlamydia trachomatis and Chlamydia pneumoniae infections and immunological markers (C-reactive protein, CRP, TNF-α, IL-6, IL-8, and IL-10) in the process of atherosclerosis." (PMID 30804931, 2019). "The positive relationship of CRP and T2DM progression probably relates to atherosclerosis development." (PMID 31485456, 2019). "So, inflammatory markers, such as C-reactive protein (CRP), interlekukin (IL), and hematologic markers, were searched as an etiology or prognostic factor in the atherosclerosis, or both." (PMID 31324033, 2019). "The cascade of events leading to atherosclerosis and CVD is complex, but macrophage influx in adipose tissue with local inflammation, release of adipokines and liver-induced CRP are important reactions." (PMID 29813131, 2018). "CRP is elevated in CAD and contributes directly to atherosclerosis via leukocyte activation and endothelial dysfunction." (PMID 29859125, 2018). "In the plasma of patients with CD, both CRP and MDA levels are found to be elevated, and their values are assumed to grow further with age, as well as in the comorbidities such as atherosclerosis." (PMID 30314292, 2018). "The released CRP binds to lipoproteins (LDL and VLDL), upregulating adhesion molecule expression and progression of atherosclerosis and MetS." (PMID 28798859, 2017). "Previously PTX3, CRP and SAP have been found in human atherosclerotic plaques and CC, similar to those found in atherosclerosis, and are known to activate the complement system and induce inflammation." (PMID 28900428, 2017).